BRAF (B-Raf proto-oncogene, serine/threonine kinase)
Diseases named in the same sentence as BRAF in open-access papers (continued):
Sharing a sentence is not in itself a finding about the gene and the disease.
cancer (continued). "Aberrant expression of TEAD has been documented to influence well‐known cancer genes such as KRAS and BRAF, with its transcriptional output implicated in various processes including cancer metabolism, tumour progression and cancer metastasis." (PMID 33570213, 2021). "This lower immunogenic state of the BRAF-resistant cells has fewer tumor infiltrating T-cells and NK cells and they are less effective at recognizing and killing the cancer cells, which are all characteristics of immunosenescence." (PMID 34066966, 2021). "Retrospective multicenter studies have demonstrated that the presence of BRAF V600E mutation is significantly associated with poorer PTC outcome and increased cancer-related mortality among patients with PTC." (PMID 34070605, 2021). "In hypermutated cancers, APC, TGFBR2, BRAF, MSH3, MSH6, SLC9A9, and TCF7L2 were highly mutated, in particular the frequent mutations of BRAF (V600E)." (PMID 33719345, 2021). "FGFR-mediated activation of the PI3K/AKT pathway is also observed in cancer cells during BRAF (serine/threonine-protein kinase B-raf) or MEK (mitogen-activated protein kinase kinase) inhibitors treatment." (PMID 34830951, 2021). "Different types of human cancers are associated with mutations in MAPK/ERK signaling pathways and the B-RAF proto-oncogene (BRAF) gene." (PMID 34680491, 2021). "BRAF mutations are associated with the abnormal regulation of microRNA, constitute the most frequent molecular alterations identified in PTC, determining cancer’s biological characteristics and the disease’s outcome." (PMID 34319022, 2021). "Oncogenic activation of BRAF enhances cancer progression by constitutively promoting RAS-independent MAPK pathway signaling." (PMID 34122331, 2021). "We further investigated the effect of KRAS or BRAF knock-down on anchorage independent growth in these cancer-derived cell lines." (PMID 33793658, 2021). "Activated KRAS binds and activates RAF family kinases (RAF1, BRAF, and ARAF), subsequently leading to uncontrolled proliferation and other processes causing cancer development and spread." (PMID 35141142, 2021). "Further experiments showed that removing the gene for NKX2-1 made these cancer cells less responsive to drugs known as BRAF/MEK inhibitors that are commonly used to treat cancer." (PMID 33821796, 2021). "BRAF alterations are important drivers of human cancer, particularly in melanoma (found in 40–50%), thyroid cancers (10–70%), colorectal cancers (10%) and NSCLC (3–5%)." (PMID 33995103, 2021). "Researchers have observed higher levels of PI3K/AKT pathway activation in CRC than those in other cancer types (even in BRAF mutated specimens), indicating a critical role of PI3K/AKT pathway in cancer." (PMID 34790119, 2021). "Specifically, the oncogenic proteins RAS, MYC, and BRAF have been shown to directly stimulate metabolic pathways by increasing the expression of key metabolic enzymes in cancer cells." (PMID 33766731, 2021). "Co-treatment of inhibition of YAP1 activity and PLX 4032 has been confirmed as a feasible treatment for BRAF-resistant melanoma derived from cancer stem cells." (PMID 33996543, 2021). "In terms of cancer genes, SBS7 caused a large number of BRAF and NRAS mutations in SKCM, and SBS10 caused some high-frequency mutations in PTEN genes in UCEC." (PMID 34901014, 2021). "Further liquid biopsy biomarkers are needed to better guide targeted therapies for BRAF mutant cancers." (PMID 33995103, 2021). "To confirm these findings, we evaluated the ability of SJF-0628 to degrade endogenously expressed BRAF mutants in cancer cells." (PMID 33568647, 2021).
cancer (continued). "Our findings indicate that within a clinical setting, double somatic genetic alterations account for almost half of dMMR cancers that remain unexplained by pathogenic or likely pathogenic germline variants, MLH1 promoter hypermethylation, or BRAF V600E." (PMID 34397043, 2021). "Inhibition of autophagy has also been assessed in combination with inhibition of PI3K→AKT→mTOR signaling in BRAF-driven cancers." (PMID 34298710, 2021). "Real-world data of 93 BRAF V600E mCRC patients from Sun Yat-sen University Cancer Center were evaluated using the prognostic factors affecting overall survival (OS)." (PMID 34572480, 2021). "However, KRAS or BRAF gain-of-function mutations are frequently observed in multiple cancer types, especially in CRC, pancreatic cancer, and non-small-cell lung cancers (NSCLC), which may hijack the function of SHP2 as the key mediator of multiple RTKs to control the ERK and AKT signaling." (PMID 34790119, 2021). "Several reports have identified oncogenic mutations in MAPK kinase 1 (MAP2K1, also called MEK1) as alternative mechanism for MAPK pathway activation in BRAF wild-type tumor in various cancers." (PMID 34046359, 2021). "This suggests that in particular cancers, for KRAS, BRAF, and NRAS, the major drivers of oncogenesis are gene mutations rather than cellular mRNA levels." (PMID 33398072, 2021). "These trials led to the approval of encorafenib plus binimetinib or cetuximab for treating advance BRAF(V600E)-harboring cancers." (PMID 35582307, 2021). "Experimental targeting of EGFR‐BRAF‐MEK in cancer organoids affected signaling and gene expression contingent on predictive KRAS/BRAF mutations and induced cell plasticity overriding default developmental trajectories." (PMID 34409732, 2021). "In this work, we use targeted protein degradation as a strategy to address mutant BRAF-driven cancer." (PMID 33568647, 2021). "Current researches showed that suppression of BRAF is a new era in human cancer therapeutic treatment." (PMID 35424523, 2021). "The accumulating body of studies showed that BRAF V600E affects cancer cells in different mechanisms." (PMID 34567185, 2021). "In line with this, MSC-1 harbored mutations in many drivers, such as ATM, BRAF, and HMCN1, which play vital roles in the tumorigenesis and development of many cancers." (PMID 33959500, 2021). "All classes of BRAF mutations are recognized as oncogenic driver mutations, yet only BRAFV600E mutations represent clinically actionable drug targets in cancer patients." (PMID 34921211, 2021). "By approaching BRAF-driven cancers by inhibiting both BRAF and MEK simultaneously, emergence of resistance significantly decreased." (PMID 34829820, 2021). "The first six included patients with prespecified tumors (NSCLC, ovarian, colorectal, and breast cancers, cholangiocarcinoma, and multiple myeloma), while the seventh cohort included other BRAF V600-mutant cancers." (PMID 34804975, 2021). "Intriguingly, besides their effect on the MAPK cell signaling pathway, BRAF/MEK inhibitors are thought to also address targets in the cancer-immunity cycle." (PMID 33804800, 2021).
cancer (continued). "Consistently, high allelic expression of RAS mutations was also associated with poorer 5-year overall survival among patients with stage II and III cancers (including only patients treated by complete resection for BRAF wild-type tumors)." (PMID 34470667, 2021). "Alectinib, crizotinib, ceritinib, brigatinib and lorlatinib for ALK-rearranged cancers, as well as dabrafenib and trametinib for BRAF V600 mutant disease." (PMID 32915318, 2021). "There are some available options of molecular targeted inhibitors for this type of cancer, like BRAF and MEK inhibitors." (PMID 34885944, 2021). "Flockhart and colleagues verified the expression profiles of BRAF-driven cancer tissue vs. non-BRAF-mutant melanocytes." (PMID 33503876, 2021). "Recently, it has suggested that mast cells (MCs), microRNAs (miRNAs), Kirsten rat sarcoma (KRAS) and v-raf murine sarcoma viral oncogene homologue B (BRAF) plat a role in cancer growth and progression." (PMID 34680251, 2021). "Across a broad panel of oncogene-driven pre-clinical models, we observed a highly conserved transcriptomic signature following kinase inhibition including induction of IFN-target genes, which was most pronounced in EGFR-driven and BRAF-driven cancers." (PMID 34535668, 2021). "To compare and differentiate similar treatments, we examined a case study of five BRAF targeted compounds under different dosages to almost 1000 cancer cell lines." (PMID 33493149, 2021). "Despite initial success of the BRAF inhibitor (BRAFi) therapies, resistance and secondary cancer often occur." (PMID 34066966, 2021). "The anticancer activity of LXH-254 is demonstrated in tumors carrying BRAF/RAS co-mutations, but it has moderate activity against cancers driven by KRAS mutants." (PMID 34607583, 2021). "This is the first study to date to systematically assess RAS dependency of BRAF alterations with real-world cancer genomic databases." (PMID 33507258, 2021). "For example, cancer cell lines with mutations in the BRAF genes are significantly more sensitive to PLX4730, a BRAF-inhibitor, than those with wild-type BRAF." (PMID 33858332, 2021). "Several studies have shown that SCH772984 inhibited BRAF/RAS-mutant cancer cells proliferation and increased apoptosis in vitro and in vivo." (PMID 34638546, 2021). "Future scrutiny will also involve CPI combination with TKI in never smoking molecular subsets beyond EGFR and ALK positive cancers, including those with BRAF V600, RET fusion and MET exon 14 who have shown promising TKI efficacy." (PMID 32915318, 2021). "In human cancer cell lines, an increase in GLUT1 expression and glucose uptake was critically dependent on KRAS or BRAF mutations." (PMID 33420213, 2021). "Surgery appears to be recommended when a molecular alteration is detected, particularly BRAF or PAX8/PPARγ which are highly specific for cancer." (PMID 32638211, 2021). "Since oncogenic alterations that aberrantly activate RAS/RAF/MEK/ERK signaling mainly occur on RAFs, particularly BRAF or upstream, this family of kinases has been considered an ideal target for cancer drug development." (PMID 35582307, 2021). "BRAF mutations are found in 8–12% of cancers, with BRAFV600E accounting for more than 90% of mutations in BRAF-mutated cancers." (PMID 34299337, 2021). "Since activating mutations in BRAF (B-Raf proto-oncogene, serine/threonine kinase) are highly oncogenic, BRAF inhibitors including dabrafenib have been developed for cancer." (PMID 34296750, 2021). "Activating the BRAF mutation is an actionable target for developing effective therapeutic agents inhibiting the BRAF/mitogen-activated protein kinase (MAPK) pathway in canine cancer as well as human cancer." (PMID 34502061, 2021).
cancer (continued). "The importance of BRAF in cancer is well-established, with a number of inhibitors in development or approved for clinical use for an increasing variety of different cancers." (PMID 34296750, 2021). "Multiple studies have demonstrated that in BRAF V600E mutant cancers, BRAF inhibition can lead to rapid EGFR-mediated feedback activation." (PMID 34071428, 2021). "After BRAF activation inhibition, cell proliferation was blocked in the G1 phase, thus affecting the cancer cell cycle." (PMID 33622273, 2021). "Combination therapy involving Lys05 and BRAF inhibitors has shown to inhibit cancer cell growth in vivo." (PMID 33802014, 2021). "Although not significant, data shows a trend to a link between diagnostic performances of genetic testing and cancer prevalence, PTC rate and proportion of PTC harbouring BRAF mutations in each cohort, especially regarding sensitivity and PPV." (PMID 32638211, 2021). "Both of them occur in more than 25% of ATCs, according to catalogue of somatic mutations in cancer (COSMIC) database, while 15.38–33.33% and 6.8–41.2% of PDTCs harbor BRAF and RAS mutations, respectively." (PMID 34206867, 2021). "In other words, once cancer cells possess a high level of active Ras, the drug-loaded BRAF(V600E) will dimerize with CRAF and trigger its catalytic activity, which has been termed as the paradoxical effect of RAF inhibitors." (PMID 35582307, 2021). "Other mutated cancer genes included those involved in Wnt signaling (APC, AMER1), mitogen signaling (KRAS, BRAF), epigenetic modification (ARID1A, ARID2, DNMT3A, NCOA3) and DNA repair (RAD50, BRIP1, ERCC5, RECQL4)." (PMID 33776923, 2021). "When looking specifically for alterations in thyroid-related genes (any reported mutation from the previous pan-exomic Cancer Genome Atlas study of 500 PTC cases), case 4 was found to harbor a BRAF V600E mutation in both primary and metastatic samples." (PMID 33827048, 2021). "Compared to BRAF fusions, BRAFV600E tends to be more aggressive, more likely to be associated with CDKN2A/B deletions, and can transform cancers into higher-grade tumors." (PMID 33980169, 2021). "Among patients in cluster 2, for example, interactions between cancer stage, grade, radiotherapy, TMB, BRAF mutation status were identified." (PMID 34600575, 2021). "BRAF rearrangements have been described in a number of different cancers, mainly (85% of the cases) in astrocytic pilocytomas, the most common childhood brain tumor." (PMID 34575554, 2021). "Problem 1 asked teams to predict molecules that bound the RETM955T-associated cancer targets RET[M918T], BRAF, SRC, S6K, and avoided binding to MKNK1, TTK, ERK8, PDK1, and PAK3." (PMID 34520464, 2021). "We further apply the model to data from five BRAF targeted compounds applied to different cancer cell lines under different dosage levels." (PMID 33493149, 2021). "Nonetheless, resistance to BRAF inhibitors and limited efficacy of the immunotherapy has prompted researchers to keep identifying novel therapeutic targets for this aggressive cancer." (PMID 33802088, 2021). "Approximately 10% of mutations in BRAF contribute to the alteration of the Ras-Raf-MEK-ERK pathway, which leads to 40% of all human cancers." (PMID 34692523, 2021). "The BRAF-V600E mutation is a significant unfavorable prognostic sign in the PTC progression, predicting the response to anti-cancer therapy and diseases’ outcome." (PMID 34319022, 2021). "Examination of KRAS and BRAF mutation statuses is indicated in metastatic cases since wildtype KRAS and BRAF carcinomas are eligible for anti-EGFR therapy." (PMID 33671994, 2021).
cancer (continued). "The choice of the initial profile was guided by biology: dual inhibitors of EGFR and ErbB2 are regarded as an advantageous treatment option for several carcinomas, whereas BRAF is a common undesired anti-target." (PMID 33530327, 2021). "All the examined carcinomas were BRAF-wildtype microsatellite stable tumors with an epithelial histological subtype." (PMID 33671994, 2021). "Altogether, BRAF mutations and RET rearrangements are termed as BRAF-like carcinomas and present similar expression patterns." (PMID 34201607, 2021). "In RAS-mutant cancer cells, BRAF inhibitors activate downstream signaling by potentiating the interaction of CRAF and RAS12." (PMID 33060766, 2020). "There is growing evidence that BRAF/MEK inhibitors target multiple events in the cancer-immunity cycle." (PMID 31947592, 2020). "Currently inhibitors of cell surface receptors or upstream kinases such as EGFR and BRAF are used as target therapy in various types of cancer and accomplish remarkable improvement in cancer treatment." (PMID 33172112, 2020). "In that case however, the authors described a role for histone hypermethylation (H3K27me3) in tumor core regions specifically, that resulted in cancer cell dedifferentiation and resistance to BRAF inhibitor treatment." (PMID 32042336, 2020). "Cancers with mutation of RAS and BRAF genes were found to be resistant to anti-EGFR (epidermal growth factor receptor) therapy." (PMID 32867793, 2020). "BRAF mutant microsatellite stable cancers are known to confer a particularly poor prognosis, in part due to the low neoantigen burden and poor immunogenicity of the cancers." (PMID 32384699, 2020). "Remarkably, the authors showed that their method is able to identify weak cancer drivers such as BRAF G466A and PI3KCA M1043I." (PMID 32144301, 2020). "Several of these BRAF inhibitors are currently used in clinical practice for specific anti-cancer therapies including CRC treatment." (PMID 35582445, 2020). "BRAF FOXE1+/− cancers show increased apoptosis, as measured by cleaved caspase-3 positive cells number." (PMID 33375029, 2020). "These are the reasons that the EGFR cascade and particularly BRAF oncogene has become of interest in various research searching for novel cancer treatments." (PMID 33247675, 2020). "Evaluation in BRAFV600E mutant cancer cells indicates that 57 can be potentially effective against BRAF mutant cancers." (PMID 33479617, 2020). "BRAF mutation is associated with activation of the MAPK pathway, which frequently plays a role in human cancers." (PMID 32637031, 2020). "The first-generation RAF inhibitors, Vemurafenib, Dabrafenib, and Encorafenib, were developed and applied to treatment of BRAF(V600E)-harboring cancers as single agents or together with MEK inhibitors." (PMID 31941155, 2020). "Major drivers of these cancers include BRAF (V600E, V599E) and/or KRAS (G12C, G12D) along the MAPK pathways while immunotherapies were considered as a monotherapy or in combination in those tumors expressing PD-1 ligands." (PMID 32260561, 2020). "In this work, we approached three human oncogenes, BRAF, KRAS, and EGFR, and studied the mutation-specific probes as duplexes with a fragment of cancer RNA." (PMID 36703315, 2020). "At present, three RAF inhibitors and three MEK inhibitors have been approved to treat late-stage BRAF(V600E)-harboring cancers as a single agent or in combination with other chemotherapeutics and exhibited excellent efficacies." (PMID 32807225, 2020). "In summary, six diarylpentanoids were synthesized and investigated for their anti-cancer potential against a panel of KRAS- and BRAF-mutated CRC cell lines." (PMID 32858795, 2020).